TARBP2 (TARBP2 subunit of RISC loading complex)
Diseases named in the same sentence as TARBP2 in open-access papers (continued):
Sharing a sentence is not in itself a finding about the gene and the disease.
adrenocortical tumors (1 paper, 2013). "Further analyses are warranted to investigate the potential nuclear role of TARBP2 and its implication in the pathogenesis of adrenocortical tumors." (PMID 23671264, 2013). "Adrenocortical tumor patients were divided into high or low mRNA levels of TARBP2, DICER, and DROSHA according to their median expression levels." (PMID 23671264, 2013). "We therefore sought to determine subcellular localization and expression of TARBP2 in adrenocortical tumors." (PMID 23671264, 2013). "This is the first study to demonstrate the deregulation of miRNA-processing factors in adrenocortical tumors and to show the clinical and biological impact of TARBP2 over-expression in this tumor type." (PMID 23671264, 2013). "We report dysregulation of miRNA machinery components in adrenocortical tumors and the potential role of TARBP2 as molecular biomarker for ACC classification." (PMID 23671264, 2013). "We analyzed the mRNA expression levels of five miRNA-processing genes (DROSHA, DGCR8, DICER, TARBP2, and PRKRA) in 73 adrenocortical tumors and nine adrenal cortices using RT-qPCR." (PMID 23671264, 2013). "We also tested the predictive potential for TARBP2 and DROSHA to detect ACCs among the 45 potentially malignant adrenocortical tumors after exclusion of tumors with sizes ≤3 cm and the seven patients presenting metastases at diagnosis." (PMID 23671264, 2013). "To confirm whether TARBP2 and DICER were biological targets of miR-195 and miR-497 in adrenocortical tumors, we transfected NCI-H295R cells with miRNA mimics (pre-miR-195 and/or pre-miR-497)." (PMID 23671264, 2013). "In our study, we show that TARBP2 is a strong predictor of carcinoma and can reliably classify ACC in a cohort of non-metastatic adrenocortical tumors." (PMID 23671264, 2013).
Cystic Nephroma (1 paper, 2024). A benign encapsulated neoplasm of the kidney, characterized by the presence of cysts separated by septa. "Mutations in this complex, including in TARBP2, lead to Dicer1 Syndrome which includes multiple rare malignancies including cystic nephromas and Sertoli-Leydig cell tumors." (PMID 39639036, 2024).
endometrial tumors (1 paper, 2021). "Of the indel hotspots in XPO5 and TARBP2 detected previously in colon, gastric, and endometrial tumors with MSI, we detected only two cases of the C insertion in the poly-C track (p.M145HfsTer13) in TARBP2: one in UCEC and one in STAD (both cancers often characterized by MSI)." (PMID 33406242, 2021).
heart failure (1 paper, 2023). Inability of the heart to pump blood at an adequate rate to meet tissue metabolic requirements. "Both molecules involved in cytoplasmic pre-microRNA processing, DICER1 (FC = −1.32, p ˂ 0.01) and TARBP2 (a gene that encodes TRBP; FC = 1.54, p ˂ 0.05), were found to be deregulated in ischemic origin heart failure observed in the patients." (PMID 37507877, 2023).
Hodgkins lymphoma (1 paper, 2015). A heterogeneous group of malignant lymphoid neoplasms of B-cell origin characterized histologically by the presence of Hodgkin and Reed-Sternberg (HRS) cells in the vast majority of cases. "Patients with Hodgkin Lymphoma that were carriers of both XPO5 AA/CC and TARBP2 TT/TC genotypes had the shortest disease free survival (p = 0.008) and overall survival (p = 0.008)." (PMID 26688807, 2015).
laryngeal carcinoma (1 paper, 2015). Carcinoma that arises from the laryngeal epithelium. "Our results suggest that rs3742330 of DICER1, rs13078 of DICER1, and rs784567 of TARBP2 as well as rs11077 of XPO5 might be associated with a risk of laryngeal cancer occurrence in the Polish population." (PMID 26688807, 2015).
larynx cancer (1 paper, 2015). A primary or metastatic malignant neoplasm involving the larynx. "This is the first report considering the association of the risk of larynx cancer and SNPs of the following polymorphisms: DROSHA (rs6877842), DGCR8 (rs3757, rs417309, and rs1640299), RAN (rs14035), XPO5 (rs11077), DICER1 (rs13078 and rs3742330), and TARBP2 (rs784567)." (PMID 26688807, 2015).
lymph node metastasis (1 paper, 2023). "Patients with DGCR8, DROSHA, and TARBP2 mutations were twice as likely to present with lymph node metastasis." (PMID 36672288, 2023). "Patients with TARBP2 gene mutation were more likely to have lymph node metastasis (OR = 2.49, 95% CI = 1.14–5.46, p = 0.022) and advanced disease stage (OR = 2.20, 95% CI = 1.08–4.46, p = 0.029)." (PMID 36672288, 2023).
migraines (1 paper, 2022). "As regards the genes TARBP2 and neuropeptide precursor of the FF-amide peptide (NPFF), these represent new candidate genes for migraine risk." (PMID 35328439, 2022). "Based on the findings of studies, there is no clear functional link between TARBP2 and migraine risk." (PMID 35328439, 2022).
ovarian tumors (1 paper, 2015). "Recently, hot-spot DICER1 mutations were found in ovarian tumors, and TARBP2 truncating mutations in tumor cell lines with microsatellite instability." (PMID 26087193, 2015).
Pleural effusion (1 paper, 2019). The presence of an excessive amount of fluid in the pleural cavity. "Consistent with our in vitro findings, TARBP2 was highly expressed in tumor cells in metastatic lymph nodes or pleural effusions compared with paired primary tumors from the same patient." (PMID 30759864, 2019). "In the paired tumor tissues, five metastatic lymph nodes or pleural effusions showed enhanced SOX2 expression compared with the corresponding primary tumors, while four of the five tissue pairs showed elevated TARBP2 expression." (PMID 30759864, 2019).
thyroid tumor (1 paper, 2019). A benign or malignant neoplasm affecting the thyroid gland. "The mutational status in the hot spot regions of DICER1, DROSHA, TARBP2, DGCR8 and the most commonly affected genes in thyroid tumors was investigated on both tumor and paired normal tissues." (PMID 30956758, 2019).
type 2 diabetes mellitus (1 paper, 2019). A type of diabetes mellitus that is characterized by insulin resistance or desensitization and increased blood glucose levels. "Our study may provide a new clue of epidemiology about the importance of miRNA processing genes (RAN, XPO5, DICER1, and TARBP2) in type 2 diabetes mellitus and diabetic vascular complications." (PMID 31354628, 2019). "The effects of RAN, XPO5, DICER1, and TARBP2 SNPs on diabetes progression were further analyzed." (PMID 31354628, 2019).
cancer (30 papers, 2013 to 2025). A tumor composed of atypical neoplastic, often pleomorphic cells that invade other tissues. "A frameshift mutation identified in human cancers disrupts TARBP2 translation, leading to defective miRNA processing and destabilization of Dicer." (PMID 41463093, 2025). "While early claims of TARBP2 mutations in cancers were later retracted, our results point to TARBP2 deficiency as a major contributor to the impaired miRNA landscape observed in myeloid malignancies." (PMID 41463093, 2025). "Decreased expression of TRBP (induced by mutation of TAR RNA-binding protein 2 (TARBP2)) is related to a destabilization of Dicer, which impairs miRNA processing in human cancer cell lines and sporadic and heredity carcinomas with microsatellite instability." (PMID 26308063, 2015). "The most interesting here was a fact of a very big difference between allele distribution in cancer and control subjects during analysis of TARBP2 rs784567 polymorphism." (PMID 26688807, 2015). "However, further studies are required to investigate the underlying molecular mechanisms of TARBP2 in human cancers." (PMID 32305960, 2020). "Trbp, also known as Tarbp2, was initially identified as an RNA-binding protein (RBP) involved in HIV pathogenesis but has also been linked to cell growth processes and cancer." (PMID 40067137, 2025). "Melo and colleagues reported that the binding of enoxacin to TARBP2 results in global miRNA profile changes, leading to notable increases in the levels of tumor-suppressive miRNAs in various cancer cells." (PMID 38689093, 2024). "Although HIF-1α and TARBP2 are both crucial for cancer development, the relationship between these two proteins remains to be clarified." (PMID 35008634, 2021). "Downregulation of miRNA processing genes (Dicer and several other proteins including Drosha, TARBP2, DGCR8 and XPO5) is an important cause for reduced levels of mature miRNAs in some cancer cells." (PMID 33917769, 2021). "To identify the downstream modulator of TARBP2, we determined the expression of several key factors that have been reported to modulate self-renewal and drug resistance of cancer cells, including SOX2, Nanog, OCT4, Lin28A, CCND1." (PMID 30759864, 2019). "Supporting this concept, the SUMOylation of TARBP2 stabilizes TARBP2 protein expression through reducing its ubiquitination to suppress tumor progression, indicating that the ubiquitination of TARBP2 is essential for cancer progression." (PMID 30657254, 2019). "This evidence proves that TARBP2 exhibits an miRNA‐independent role in regulating cancer progression." (PMID 30657254, 2019). "Transactivation response element RNA‐binding protein 2 (TARBP2) is a multifaceted miRNA biogenesis factor that regulates cancer stem cell (CSC) properties." (PMID 30657254, 2019). "Enoxacin has been previously reported to inhibit the growth of cancer cells by enhancing miRNA processing through a direct physical interaction with TARBP2 miRNA." (PMID 29467169, 2018). "Small molecule fluoroquinolone drug enoxacin was able to effectively restore TARBP2-mediated miRNA processing in a panel of cancer cell lines from several common malignancies and had a cancer-specific inhibitory effect on cell growth both in vitro and in vivo." (PMID 28973015, 2017). "Noteworthy, the four carcinomas with TARBP2 copy number gain and low TARBP2 expression exhibited high expression of miR-195 and miR-497." (PMID 23671264, 2013). "In contrast, TARBP2 has been shown to be differentially expressed in various cancers." (PMID 38689093, 2024). "Based on this report, it was confirmed that the expression of TARBP2-dependent miRNAs (miR-143 and miR-145) was inversely correlated with stemness features; thereby the potential as a therapeutic target was validated in cancers." (PMID 38689093, 2024).
cancer (continued). "Although previous studies have implicated TARBP2 in various cellular processes such as miRNA maturation, or as a mediator for different pathways, its role in cancer development has been controversial and not been established in HCC yet." (PMID 34249676, 2021). "Decreased expression of TARBP2 results in miRNA decreases in human cancers." (PMID 32305960, 2020). "In contrast, TARBP2 is overexpressed in cutaneous melanoma, adrenocortical carcinoma, and metastatic breast and prostate cancers, suggesting its specific pivotal role in different cancer types." (PMID 32138313, 2020). "TARBP2 expression was observed to be significantly elevated in most cancer types." (PMID 30657254, 2019). "As a component of RISC with Dicer and Ago2, TARBP2 might be degraded in cancer cells via selective autophagy." (PMID 30657254, 2019). "However, the E3 ligase of TARBP2 and ubiquitination levels need to be determined for further investigation in cancer." (PMID 30657254, 2019). "Furthermore, TARBP2-dependent miRNAs, miRNA-143 and miRNA-145, restrict development and tumor growth in cancer stem cells of Ewing sarcoma family tumor." (PMID 26308063, 2015). "However, miR-497 can also attenuate the malignancy of cancers by regulating other targets, such as TARBP2, DICER, BCL2, CCND1, CCNE1, CDC25A, CCND3, CDK4." (PMID 24667580, 2014). "On the other hand, we found TARBP2 gene copy number gain in 57% (16/28) of the carcinomas, suggesting that copy number gain of TARBP2 gene may be, at least partially, responsible for its over-expression in ACC." (PMID 23671264, 2013). "TARBP2 over-expression was not related to gene mutations; however, copy number gain of the TARBP2 gene was observed in 57% of the carcinomas analyzed." (PMID 23671264, 2013). "Apart from TARBP2 and RAN, our trial sequential analysis results showed that the cumulative evidence for miRNA gene machinery variants was inadequate, and additional primary allelic discrimination studies for the other nine genes are warranted to validate the outcomes in various types of cancers." (PMID 36672288, 2023). "Accumulating evidence indicates that some cancers and tumor cells are characterized by reductions in the levels of mature miRNAs compared to normal tissues or cells, which is due to reduced expression of Dicer and several other miRNA processing proteins (Drosha, TARBP2, DGCR8 and XPO5)." (PMID 33917769, 2021). "First, it is unclear whether tamoxifen-induced TARBP2 contributes to cancer metastasis." (PMID 30759864, 2019). "They showed that TARBP2 can facilitate miR-145 maturation, leading to repressed expression of the miR-145 target SERPINE1 and affecting cancer progression mediated by the HIF-1 signaling pathway." (PMID 38689093, 2024). "We analyzed the mRNA expression levels of miRNA machinery components (DROSHA, DGCR8, XPO5, RAN, DICER, TARBP2, and AGO2) utilizing mRNA-Seq data from The Cancer Genome Atlas (TCGA) and The Genotype-Tissue Expression (GTEx) projects." (PMID 39404265, 2024). "As a subunit in RISC complex, TARBP2 plays significant roles in many biological and pathological conditions, including viral expression of HIV-1, microsatellite instability, cancer stem cell properties, and tumor progression." (PMID 38806480, 2024). "Using western blot and immunohistochemistry analyses, we confirmed the higher expression of TARBP2, DICER, and DROSHA at the protein level in carcinoma cases." (PMID 23671264, 2013). "De Vito and colleagues reported that TARBP2 depletion in Ewing sarcoma family tumor (ESFT) cells can promote self-renewal capacity and tumorigenesis by changing the miRNA profiles of these cells to be similar to those of ESFT cancer stem cells." (PMID 38689093, 2024). "In TARBP2high tumors, HIF-1α expression was found to be higher than that in TARBP2low tumors, thereby suggesting that TARBP2 may serve as a crucial protein regulator of HIF-1α and exhibit an oncogenic role in cancer progression." (PMID 35008634, 2021).
cancer (continued). "The microRNA (miRNA) expression levels are globally suppressed in human cancer compared to those in normal tissues, which are mostly contributed to genetic and epigenetic alterations in miRNA-processing machinery components such as DROSHA, DGCR8, XPO5, TARBP2, DICER, and AGO2 in human cancer." (PMID 30305728, 2019). "Moreover, pan-cancer studies have identified significant variations in the expression of miRNA-processing genes, including DICER1, DGCR8, and TARBP2, across multiple malignancies, reinforcing the importance of miRNA biogenesis defects in neoplastic progression." (PMID 41463093, 2025). "For example, genetic aberrations of cancer-associated genes belonging to the miRNA processing protein complex, such as TARBP2, DICER1, and XPO5, are of crucial importance in the cellular transformation pathways and contribute to an overall miRNA dysregulation in cancer." (PMID 38003902, 2023). "Our results demonstrated that suppression of TARBP2 expression promoted sorafenib resistance in HCC cells, and downregulation of TARBP2 was correlated with poor outcomes in patients with HCC, suggesting that miRNA biogenesis factors are globally repressed in HCC cancer progression." (PMID 30657254, 2019). "Together, variation of TARBP2, DICER, and DROSHA expression levels among different tumor types suggests that deregulation of miRNA-processing factors can be dependent on cellular context and imply their possible dual role as tumor suppressors or oncogenes in human cancers." (PMID 23671264, 2013). "Moreover, for carcinoma cases, we did not observe any significant association between DROSHA, DGCR8, DICER, TARBP2, or PRKRA mRNA levels and clinical–histopathological parameters such as gender, age, tumor size, or presence of metastasis (data not shown)." (PMID 23671264, 2013). "Additionally, TARBP2 acts as a dsRNA‐dependent protein kinase (PKR) inhibitor to suppress the phosphorylation of eIF2α, thus enhancing cell mitosis and destabilizing transcripts to promote cancer metastasis, exhibiting miRNA‐independent properties in regulating cancer." (PMID 30657254, 2019). "Based on these observations, we conclude that the growth effects of enoxacin on transformed MEFs are independent of TARBP2 or PRKRA and that enoxacin may act through a mechanism in transformed MEFs that is different to that in cancer cells." (PMID 29467169, 2018).